HGF (hepatocyte growth factor)
Diseases named in the same sentence as HGF in open-access papers (continued):
Sharing a sentence is not in itself a finding about the gene and the disease.
pancreatic cancer (continued). "For instances, irradiation of stromal cells could affect the invasive phenotype of pancreatic cancer through secreting HGF and other growth factors to modify tumor-stromal interactions." (PMID 26790152, 2016). "We propose that an in-depth analysis of the HGF/c-MET signaling system in pancreatic cancer could bridge the gap between basic biology and translational medicine." (PMID 26404380, 2015). "Additionally, HGF exerted a resistance to anoikis on pancreatic cancer cells by phosphorylating Akt and also promoting invasion and metastasis." (PMID 26404380, 2015). "Treatment of pancreatic cancer cells with HGF stimulated cell growth by enhancing TGF-α level." (PMID 26404380, 2015). "While their association with HGF has not been fully elucidated in pancreatic cancer, what is understood is that the expression of IL-1α by pancreatic cancer cell lines promotes HGF production in stromal cells to facilitate tumor-promoting properties." (PMID 26404380, 2015). "In the present study, we assessed the anti-neoplastic activity of targeting cMET with INC280 in pancreatic cancer models and found substantial in vitro inhibition of HGF-induced cancer cell motility and –signaling, as well as reversal of resistance-mediating properties." (PMID 25884642, 2015). "Furthermore, a study found that pancreatic cancer cells might mediate ferroptosis resistance in pancreatic cancer and activate pancreatic stellate cells, encouraging their production of HGF and increasing their antioxidant capacity." (PMID 41439136, 2026). "Therefore, targeting the MET/HGF pathway could be an option for adjuvant therapy in pancreatic cancer." (PMID 37835402, 2023). "The panel tested for the presence cfDNA KRAS mutations and serum levels of CA19-9, CEA, HGF and OPN—protein markers that are used clinically to follow pancreatic cancer patient treatment course or have been previously found to be dysregulated in pancreatic cancer patients." (PMID 34968245, 2021). "However, based on our published work with the early model of pancreatic cancer, and on the current in vitro data, it is likely that dual inhibition of HGF and c-MET can block/prevent the occurrence of new metastases, but has little effect on established metastasis." (PMID 32203220, 2020). "Moreover, the MET/HGF co-targeting may represent an option as an adjuvant therapy in pancreatic cancer." (PMID 30544501, 2018). "In addition, since TGFβ has an inhibitory role in the regulation of IL-1α-mediated cross-talk between pancreatic cancer cells and PSCs we also examined how IL-1α and TGFβ can modulate the level of HGF expressed by the PSCs and how this affects cancer cell DNA synthesis and migration." (PMID 29069737, 2017). "Furthermore, the overexpression of several angiogenic factors, such as endothelial growth factor, transforming growth factor-α, hepatocyte growth factor, fibroblast growth factor, and platelet-derived growth factor-β, has been reported in pancreatic cancer 22,23." (PMID 25914189, 2015). "Another promising therapy, NK4, an intra-molecular fragment of HGF, has been shown to possess anti-growth, anti-metastasis, anti-angiogenic abilities in addition to showing reduction in ascites, thereby prolonging survival in an orthotopic mouse model of pancreatic cancer." (PMID 26404380, 2015). "This review offers an in-depth exploration of the HGF/c-MET signaling pathway, trametinib’s mechanism, clinical applications, combination strategies, and future directions in the context of pancreatic cancer." (PMID 38473413, 2024). "The study revealed that HGF/c-MET dual inhibition curtailed angiogenesis and reduced the number of circulating pancreatic tumor cells." (PMID 39664377, 2024). "HGF is produced by pancreatic stellate cells, and its receptor, c-MET, is expressed in pancreatic cancer cells and endothelial cells." (PMID 38473413, 2024).
pancreatic cancer (continued). "In pancreatic cancer cells, which express relatively high levels of NRP1, the suppression of endogenous NRP1 completely abolished HGF-mediated cell invasion." (PMID 39769452, 2024). "In PDAC patients, pancreatic stellate cells (PSCs) produce hepatocyte growth factor (HGF) and pancreatic cancer cells express MET." (PMID 39000029, 2024). "miR-494 plays a tumor-suppressive role in pancreatic cancer and inhibits EMT invasion and migration of cancerous cells via TGF-β/SMAD and hepatocyte growth factor (HGF)/MET signaling pathways." (PMID 38559560, 2024). "The critical role of the HGF/c-MET pathway in terms of its mitogenic and motogenic effects on cancer cells has been reported in several cancers, including pancreatic cancer." (PMID 38473413, 2024). "We previously demonstrated that concomitant targeting of HGF and MET allows optimal blockage of the ligand/receptor axis, strongly reducing the metastatic spreading of pancreatic cancer cells." (PMID 37345079, 2023). "In pancreatic cancer, MET serves as both a marker and therapeutic target for CSCs,147 Additionally, the interaction between HGF/MET and tumor‐stromal cells helps to maintain the preferred glucose metabolism of pancreatic tumor stem cells." (PMID 38077251, 2023). "Through interactions with the HGF/MET signaling pathway in the tumor microenvironment, we can expect savolitinib to be particularly effective in pancreatic cancer." (PMID 37835402, 2023). "HGF is produced by PSCs, while its receptor MET is present in pancreatic cancer cells and endothelial cells." (PMID 37835402, 2023). "Studies investigating the HGF/MET pathway have been conducted in various cancer types, including NSCLC, breast cancer, head and neck cancer, colorectal cancer, gastric cancer, pancreatic cancer, and other gastrointestinal cancers." (PMID 37835402, 2023). "MRC5 fibroblast cells cultivated in hypoxia secrete hepatocyte growth factor (HGF) to increase c-Met phosphorylation and invasiveness of PK8 pancreatic cancer cells." (PMID 35884382, 2022). "Activated PSCs secreted HGF, which resulted in increased c-mesenchymal-epithelial transition (c-MET) expression and enhanced antioxidant capacity in pancreatic cancer cells." (PMID 35693705, 2022). "Mechanistically, activated PSCs secreted HGF, which further activated the HGF receptor, c-MET, in pancreatic cancer cells, prevented lipid peroxidation, and ultimately triggered pancreatic cancer cell ferroptosis resistance in vitro and in vivo." (PMID 35693705, 2022). "HGF/MET signaling promotes CSC properties by inducing YAP nuclear translocation and HIF-1α stabilization in pancreas cancer." (PMID 34439392, 2021). "HGF is produced by PSCs and its receptor c-MET is expressed on pancreatic cancer cells and endothelial cells." (PMID 33271944, 2020). "There have been some encouraging data pertinent to HGF and/or c-MET inhibitors in clinical trials (mostly phase I/II trials) in several non-pancreatic cancers." (PMID 33271944, 2020). "Gene expression data from the cancer cell line encyclopedia (CCLE) assessing global Met expression along with its ligand, HGF, and other downstream kinases (MAPK1, AKT2, and AKT3) supported high Met expression in pancreatic cancer cell lines." (PMID 31903112, 2020). "A variety of cell signaling pathways play well-known roles in pancreatic cancer, including WNT/β-catenin, TGF-β, NF-κB, and HGF signaling pathways." (PMID 32670371, 2020). "Driver genes have been identified as the building blocks in pancreatic cancer, and emerging data suggested that driver gene K-Ras involved in the process of splicing control, such as mucin 6 (MUC6), hepatocyte growth factor (HGF), VEGFR-2, and VEGFB." (PMID 31552163, 2019). "Here, we discuss the role of the MET/HGF axis in tumor progression and dissemination considering as a model pancreatic cancer, and provide a proof of concept for the application of dual MET/HGF inhibition as an adjuvant therapy in pancreatic cancer patients." (PMID 30544501, 2018).
pancreatic cancer (continued). "On one side, MET has been identified as a marker of pancreatic cancer stem cells (CSCs), and on the other the MET/HGF axis supports the mesenchymal network." (PMID 30544501, 2018). "We also conducted subgroup analyses for the different tumor entities and the correlation between HGF levels and OS was significant for the two larger groups NSCLC (n = 122; p-value = 0.0012) and pancreatic cancer (n = 41; p-value = 0.00014)." (PMID 28456787, 2017). "Pancreatic cancer cells themselves secrete a number of mitogenic factors with angiogenic properties, such as EGF, TGF-α, HGF, FGF-1, 2, and 5, and PDGF-β." (PMID 26404380, 2015). "With such compelling evidence, NK4 is a plausible option to target HGF along with c-MET and other drugs currently in use for controlling pancreatic cancer." (PMID 26404380, 2015). "This review will focus on the role of hepatocyte growth factor (HGF), also referred to as scatter factor (SF), as a therapeutic target in the treatment of pancreatic cancer." (PMID 26404380, 2015). "Consistent with this, Tomioka and colleagues reported that treatment with the recombinant HGF antagonist NK4 inhibited orthotopic tumor growth and dissemination in vivo and decreased MVD in pancreatic tumors." (PMID 22815748, 2012). "Although weak mitogenic activity of HGF was seen only in SUIT-2 and KP-3 cells, HGF strongly stimulated migration and invasion of these pancreatic cancer cells, except for BxPC-3 and MIA PaCa-2 cells." (PMID 11259105, 2001). "The HGF/c-MET (mesenchymal–epithelial transition factor) pathway is emerging as a key area of focus in understanding and potentially disrupting the intricate cellular interaction that results in pancreatic cancer’s aggressiveness and resistance to treatment." (PMID 38473413, 2024). "Non-chemokine agents, such as HGF, stimulate the migration of ovarian cancer cells, while IL-6 supports this process in pancreatic cancer cells." (PMID 39595551, 2024). "The HGF/MET/CD44v6 signaling pathway promotes tumor growth and metastasis in pancreatic cancer." (PMID 39769452, 2024). "We previously demonstrated that the combination of a MET-targeting antibody (MvDN30) with an HGF-sequestering protein (DecoyMETK842E) strongly inhibits the HGF/MET axis in HPAF-II cells, resulting in a dramatic reduction in the ability of pancreatic cancer cells to metastasize to the lungs." (PMID 34298732, 2021). "Further, the HGF-MET axis is involved in the metastatic progression of pancreatic cancer and functions as a bridge linking the tumor with stroma, resulting in a positive loop for pancreatic cancer progression." (PMID 34479614, 2021). "Binding of HGF to MET activates several signaling pathways, including MAPK and PI3K, which regulate the proliferation, invasion, and migration of cancer cells, including pancreatic cancer." (PMID 32670371, 2020). "The authors envision that a novel antiangiogenic approach that targets the HGF/c-MET and uPA pathways could be used against pancreatic cancer." (PMID 32116785, 2020). "The hepatocyte growth factor and its receptor, c-MET play an important role in cancer progression (as discussed in detail below), and this pathway warrants investigation for its role in pancreatic cancer." (PMID 33271944, 2020). "Treatment of pancreatic cancer cells with HGF or serum did not have a considerable effect in inducing the dephosphorylation of CAP1 (shown for PANC-1 cells)." (PMID 30894654, 2019). "HGF-MET signaling may play an important role in the invasion and metastasis of pancreatic cancer cells." (PMID 31867280, 2019). "Additionally, activated PSCs play a vital role in the pancreatic cancer microenvironment by secreting molecules such as TGFβ, IL-6, stromal cell-derived factor-1 (SDF-1), hepatocyte growth factor (HGF) and galectin-1 to promote pancreatic cancer progression." (PMID 30060755, 2018).
pancreatic cancer (continued). "In pancreatic tumor progression, cross-talk between PSC and PC is mediated through several growth factors including platelet-derived growth factor, transforming growth factor, vascular endothelial growth factor and hepatocyte growth factor (HGF)." (PMID 30567565, 2018). "Having established that PAK4 is expressed in pancreatic cancer cells and that those cells with high expression of PAK4 also have a migratory response to HGF we sought to establish whether PAK4 expression was required for the migratory response to HGF." (PMID 28205613, 2017). "HGF is produced by PSCs and its receptor c-MET is expressed on pancreatic cancer cells." (PMID 29100344, 2017). "In the present study, we have isolated primary pancreatic stellate cells from eight different human pancreatic adenocarcinomas and studied their effects on pancreatic cancer cells, particularly the role of PSC-derived HGF in stimulation of proliferation and migration." (PMID 29069737, 2017). "Over-expression of HGF and c-MET was detected in a high proportion of pancreatic cancer." (PMID 25909285, 2015). "Interestingly, the hepatocyte growth factor (HGF) has been identified recently as an additional ligand for NRP1, which potentiated HGF/c-Met signalling and promoted glioma progression and pancreatic cancer cell invasion." (PMID 20087344, 2010). "Both hepatic stellate cells, the main source of myofibroblastic CAFs, and all other CAFs promote tumor metastatic growth and mortality of desmoplastic CRCs and pancreatic cancer liver metastases through secreted hyaluronan and HGF, but not those of non-desmoplastic tumors." (PMID 37046676, 2023). "Moreover, inhibition of the HGF/MET axis could be combined with chemotherapeutics agents, as proposed in a preclinical study for pancreatic cancer treatment." (PMID 37345079, 2023). "Thus, blocking the HGF/c-Met/mTOR signaling pathway can inhibit cancer cells invading and migrating along nerves and may be a therapeutic target for PNI in pancreatic cancer." (PMID 35449152, 2022). "Another in vitro study demonstrated the invasiveness of a pancreatic cancer cell line (PK8) that was enhanced by conditioned medium from fibroblast cell line (MRC5) under hypoxic conditions; importantly this effect was reduced by neutralizing HGF in the conditioned medium." (PMID 33271944, 2020). "Notably, HGF/c-MET inhibition has been shown in preclinical models to increase drug delivery and improve chemotherapeutic response both in genetically engineered mouse models and orthotopic models of pancreatic cancer." (PMID 33271944, 2020). "Although this model is not related to pancreatic cancer, examining the effect of A platensis on HGF/c‐Met‐Ras and Raf‐mediated ERK activation could help to assess the mechanisms of A platensis impact on the ERK pathway." (PMID 31957261, 2020). "Again, such explicit evidence as is seen with prostate cancer is lacking in pancreatic tumor research, and whether the acidic environment can activate the HGF-c-MET pathway needs further investigation." (PMID 26404380, 2015). "Given the potential clinical benefit for addition of ficlatuzumab to cytotoxic therapy, further evaluation of HGF/c-Met pathway inhibitors may be warranted in patients with pancreatic cancer, although alternate cytotoxic backbones that do not induce additive peripheral edema may be preferable." (PMID 36807743, 2023). "In colonic epithelial cells, both HGF and KGF are enhanced in IL-1 stimulated production of IL-8 during mucosal inflammations, and IL-8 expression, although promoted as an angiogenic factor in pancreatic tumors, might be playing a significant role in supporting this tumor microenvironment." (PMID 26404380, 2015). "However, Qian and colleagues have demonstrated in vitro that patient tumour derived fibroblasts expressing HGF could initiate an apparent invasion-stimulating response in pancreatic cancer cells with high expression of c-MET but not in cells with low expression of c-MET." (PMID 33271944, 2020).
pancreatic cancer (continued). "Thus, we submit that a therapeutic strategy involving HGF/c-MET inhibition with or without chemotherapy, is eminently ready to be taken to clinical trials for pancreatic cancer in both neoadjuvant and adjuvant scenarios." (PMID 33271944, 2020). "We believe that the MSP–RON signaling pathway, but not the HGF–MET signaling pathway, may be the dominant mechanism in pancreatic cancer." (PMID 31867280, 2019). "While present knowledge of HGF/c-MET has supported clinical trials targeting various aspects of the biological mechanism, more mature studies addressing side effects and clinical outcomes specific to pancreatic cancer are lacking." (PMID 26404380, 2015).